ENSG00000299328 (novel transcript)
Gene: Long non-coding RNA gene on chromosome 1 (148,263,272 to 148,279,083, forward strand). Ensembl gene ENSG00000299328.
Gene Ontology:
Molecular function: triplet codon-amino acid adaptor activity
Biological process: translation